SYPL2 (synaptophysin like 2)
Description:
Involved in communication between the T-tubular and junctional sarcoplasmic reticulum (SR) membranes.
Synonyms: Mg29
Tractability: Antibody: UniProt predicts a signal peptide or a membrane-spanning region; the Human Protein Atlas places it where antibodies can reach.
Gene: Protein-coding gene on chromosome 1 (109,466,542 to 109,482,134, forward strand). Ensembl gene ENSG00000143028.
Subcellular location: Membrane
Subcellular location (Human Protein Atlas): Cytosol; Plasma membrane
Gene Ontology:
Biological process: substantia nigra development
Cellular component: synaptic vesicle membrane; membrane; synaptic vesicle
Genetic constraint (gnomAD): Loss-of-function variants: 24 observed, 29.66 expected, observed/expected ratio (o/e) 0.81, 90% interval 0.58 to 1.14. The upper end of that interval is the gene's LOEUF score, 1.14, which puts it in group 4 of 6, group 1 being the genes least tolerant of losing a copy. Missense variants: 342 observed, 361.9 expected, observed/expected ratio (o/e) 0.95, 90% interval 0.86 to 1.03. Synonymous variants: 144 observed, 138.96 expected, observed/expected ratio (o/e) 1.04, 90% interval 0.9 to 1.19.
Homologues: Orthologues: chimpanzee SYPL2 (100% identical), macaque SYPL2 (99% identical), dog SYPL2 (92% identical), guinea pig SYPL2 (92% identical), mouse Sypl2 (91% identical), rabbit SYPL2 (90% identical), pig SYPL2 (90% identical), rat Sypl2 (81% identical), tropical clawed frog sypl2 (55% identical), zebrafish sypl2b (40% identical), zebrafish sypl2a (36% identical), Caenorhabditis elegans sph-1 (19% identical). Paralogues in human: SYNPR (45% identical), SYP (43% identical), SYPL1 (34% identical).
Diseases named in the same sentence as SYPL2 in open-access papers:
SYPL2 is named in the same sentence as 12 diseases in open-access papers, as found by Europe PMC text mining. Sharing a sentence is not in itself a finding about the gene and the disease. The quoted sentences say what the papers report.
renal dysfunction (2 papers, 2021 to 2024). "A variant in A1CF (rs10994860) protected against hyperfiltration and renal dysfunction (beta −0.69852, p = 0.020), whereas a variant in SYPL2 (rs12136063) was associated with an increased risk (beta 0.57907, p = 0.04208)." (PMID 38791464, 2024). "However, SYPL2-rs12136063 as well as APOL1 (G1)-rs73885319 conferred increased risk of progressing to the renal dysfunction or to prevalent glomerular hyperfiltration, explaining 11.04 and 0.97% of status changes, respectively." (PMID 33790942, 2021). "This study has replicated APOL1 gene variants: (G1)-rs73885319 and (G2)-rs71785313, shown to be strongly associated with renal dysfunction in SCD patients, as well as A1CF-rs10994860, SYPL2-rs12136063, WNT7A-rs6795744, and TMEM60-rs6465825 in Cameroonian SCD patients." (PMID 33790942, 2021).
cerebral infarct (1 paper, 2012). "Most of these data seem to suggest acute inhibition of neurogenesis, but the SYPL2 gene (Synaptophysin-like-2) and the neurogenesis marker DPYSL3 (TUC-4) were augmented in the core at 3 d after cerebral infarct, probably reflecting early brain repair responses after damage." (PMID 23284893, 2012).
depression (1 paper, 2021). "Interestingly, its paralog SYPL2 has been associated with morbid obesity and depression." (PMID 33710394, 2021).
heart failure (1 paper, 2017). Inability of the heart to pump blood at an adequate rate to meet tissue metabolic requirements. "The induction of Mg29 expression observed in Csrp3−/− mice was clearly of functional importance as deletion of the Sypl2 gene further reduced t-tubule structure and organization and it worsened heart failure in Csrp3−/− mice." (PMID 28706255, 2017).
melanoma (1 paper, 2020). A malignant, usually aggressive tumor composed of atypical, neoplastic melanocytes. "Next, we validated the highest significantly down- (Myh2, Mybh, Sypl2, Xirp1, Mybpc1) and up- (Fcgbp, Areg) regulated genes, including the melanoma-specific genes (Dmnt1 and Nrp2) identified by RNA sequencing following treatment with SAM+anti-PD-1 by RT-qPCR." (PMID 32983966, 2020).
SYPL2 also shares sentences with these, for which no sentence is quoted: cancer (1 paper); cardiac disease (1); dilated cardiomyopathy (1); lupus (1); lupus nephritis (1); morbid obesity (1); myocardial infarction (1).